IMP3 (IMP U3 small nucleolar ribonucleoprotein 3)
Diseases named in the same sentence as IMP3 in open-access papers (continued):
Sharing a sentence is not in itself a finding about the gene and the disease.
adenocarcinoma (7 papers, 2012 to 2024). A common cancer characterized by the presence of malignant glandular cells. "IMP3 expression levels in esophageal adenocarcinoma are significantly associated with the depth of invasion in the context of T1a or T1b adenocarcinomas." (PMID 34006250, 2021). "Although only three patients experienced infiltrating T1 adenocarcinoma into the sphincter of Oddi, Two of the three patients had a high rate of IMP3 cell positivity (0%, 50% and 70%)." (PMID 34006250, 2021). "The IMP3-positive cell rates in patients with T3 adenocarcinoma who died during the study were high (20%, 80%, and 90%)." (PMID 34006250, 2021). "In addition to IMP3-positive cell rate, poorly differentiated adenocarcinoma (log-rank test P = 0.02) and lymphatic invasion (log-rank test P = 0.038) were significantly related to prognosis in the univariate analysis." (PMID 34006250, 2021). "Specifically, the percentage of IMP3-positive cells was low in resected specimens of adenocarcinoma without infiltration into the sphincter of Oddi, whereas this percentage was notably increased in adenocarcinoma specimens accompanied by infiltration into the sphincter of Oddi." (PMID 34006250, 2021). "We were interested whether distant metastases are associated with IMP3 overexpression, regardless of the histologic subtype of adenocarcinoma." (PMID 23190601, 2012). "We investigated the relationship between the presence or absence of invasion into the lymphatic and veins and the IMP3-positive cell rate among patients with adenocarcinoma." (PMID 34006250, 2021). "IMP3 protein expression exhibited a strict nuclear staining pattern in the NSCLC tissues upon immunohistochemistry analysis, with the exception of three cases of adenocarcinoma, which showed a mainly cytoplasmic staining pattern." (PMID 25789070, 2015).
benign tumors (4 papers, 2020 to 2023). "An increased IMP3 expression was observed in both malignant and benign neoplasm." (PMID 37627115, 2023).
infection (2 papers, 2021 to 2022). The state of being infected such as from the introduction of a foreign agent such as serum, vaccine, antigenic substance or organism. "In order to confirm the role of IMP3 in modulating re‐endothelialization after carotid artery injury, we employed AAV2‐IMP3 infection to C57/BL6 mice—mice that were used to establish carotid artery injury model." (PMID 35315195, 2022).
head and neck tumors (1 paper, 2021). "However, only a few studies have assessed the role of IMP3 in head and neck tumors, and none have assessed its expression in sinonasal tumors." (PMID 33680717, 2021).
IMP3 also shares sentences with these, for which no sentence is quoted: gastric cancer (3 papers); chronic pancreatitis (2); endometrioid carcinomas (2); anaplastic large cell lymphoma (1); angiosarcoma (1); atypical endometrial hyperplasia (1); bladder cancer (1); Burkitt lymphoma (1); chronic cholecystitis (1); colon (1); cutaneous squamous cell carcinoma (1); diffuse large B-cell lymphoma (1); endometrial neoplasm (1); endometrioid endometrial carcinomas (1); epithelioid hemangioendothelioma (1); follicular lymphoma (1); gastric adenocarcinoma (1); gynecological tumors (1); head and neck squamous cell carcinoma (1); intestinal polyp (1); invasive carcinoma (1); inverted papilloma (1); leiomyoma (1); lung (1); mesothelioma (1); mucinous carcinomas (1); mucinous tumors (1); mucoepidermoid carcinoma (1); papilloma (1); peritoneal mesothelioma (1).
A further 12 diseases each share a sentence with IMP3 in 1 paper.